KRTAP4-3 (keratin associated protein 4-3)
Description:
In the hair cortex, hair keratin intermediate filaments are embedded in an interfilamentous matrix, consisting of hair keratin-associated proteins (KRTAP), which are essential for the formation of a rigid and resistant hair shaft through their extensive disulfide bond cross-linking with abundant cysteine residues of hair keratins. The matrix proteins include the high-sulfur and high-glycine-tyrosine keratins.
Synonyms: KAP4.3
Tractability: No criterion of Open Targets' tractability assessment is met for any kind of drug.
Gene: Protein-coding gene on chromosome 17 (41,167,231 to 41,168,221, reverse strand). Ensembl gene ENSG00000196156.
Pathways (Reactome):
Developmental Biology: Keratinization
Gene Ontology:
Biological process: hair cycle
Cellular component: cytosol; keratin filament
Genetic constraint (gnomAD): Loss-of-function variants: 2 observed, 0.84 expected, observed/expected ratio (o/e) 2.4. That is too few expected variants to judge how well the gene tolerates losing a copy. Missense variants: 182 observed, 210.37 expected, observed/expected ratio (o/e) 0.87, 90% interval 0.77 to 0.98. Synonymous variants: 63 observed, 72.32 expected, observed/expected ratio (o/e) 0.87, 90% interval 0.71 to 1.07.
Homologues: Orthologues: chimpanzee KRTAP4-3 (96% identical), mouse Krtap4-22 (72% identical), mouse Krtap4-26 (69% identical), mouse Krtap4-8 (67% identical), rat AABR07030464.1 (66% identical), mouse Krtap4-23 (64% identical), mouse Krtap4-6 (64% identical), mouse Krtap4-9 (63% identical), mouse Krtap4-21 (58% identical), mouse Krtap4-20 (58% identical), mouse Krtap4-13 (54% identical), mouse Krtap4-1 (53% identical), and 4 more. Paralogues in human: KRTAP4-12 (66% identical), KRTAP4-11 (66% identical), KRTAP4-5 (65% identical), KRTAP4-6 (65% identical), KRTAP4-9 (61% identical), KRTAP4-7 (56% identical), KRTAP4-8 (56% identical), KRTAP4-4 (56% identical), KRTAP4-2 (50% identical), KRTAP4-1 (50% identical), KRTAP10-7 (47% identical), KRTAP10-11 (46% identical), and 35 more.
Diseases named in the same sentence as KRTAP4-3 in open-access papers:
KRTAP4-3 is named in the same sentence as 1 disease in open-access papers, as found by Europe PMC text mining. Sharing a sentence is not in itself a finding about the gene and the disease. The quoted sentences say what the papers report.
tumor (1 paper, 2023). "However, specific mechanisms about how KRTAP4-3 affects tumor progression have not been elucidated." (PMID 37564213, 2023).